NLRP3 (NLR family pyrin domain containing 3)
Diseases named in the same sentence as NLRP3 in open-access papers (continued):
Sharing a sentence is not in itself a finding about the gene and the disease.
viral infection (continued). "Among all inflammasomes, the NOD-like receptor (NLR) family pyrin domain-containing 3 (NLRP3) inflammasome is mostly involved in inflammation, and pyroptosis are ensured due to viral infections." (PMID 33193115, 2020). "Numerous studies have established the activation of NLRP3 inflammasome by viruses with in vivo relevance for control of virus infection." (PMID 33014899, 2020). "In this review, we will focus on the recent research advances made in terms of NLRP3 inflammasome activation during a viral infection and the immune evasion mechanisms of viruses that target the NLRP3 inflammasome." (PMID 32133002, 2020). "NLRP3 is a new prognostic marker in oncology and acts as a key player in immune-related events involving bacterial and viral infection as well as autoimmune diseases." (PMID 33096896, 2020). "NLRP3 and MyD88 induce the release of IL-1 and hs-CRP, and several studies associated NLRP3 activation in multiorgan damages of virus infection." (PMID 33182653, 2020). "Although the NLRP3 inflammasome provides the host antiviral status, irregular NLRP3 inflammasome activation leads to severity of pathological injury during virus infection." (PMID 33014899, 2020). "Treatment of NLRP3 inflammasome-deficient cells with G10 enhanced type I IFN expression and effectively inhibited viral infection." (PMID 33072119, 2020). "In severe fever with thrombocytopenia syndrome (SFTS) virus infection, the cytosolic mtDNA binds and triggers NLRP3 inflammasome activation resulting in SFTS disease progression and fatal outcome." (PMID 33551822, 2020). "Viral components as well as several stimuli by virus infection are sensed by host innate immune system and activate NLRP3 inflammasome." (PMID 33014899, 2020). "Many viruses infection can induce the secretion of IL-1β to promote the development of severe inflammatory disease by activating NLRP3 inflammasome, including DENV, JEV, influenza virus, and human immunodeficiency virus type 1 (HIV)." (PMID 31474993, 2019). "More importantly, our study identified Bcl-2 as a negative regulator of ZIKV-induced NLRP3 inflammasome activation and renal cell apoptosis, which provided a new insight of the therapeutic target for renal diseases induced by viral infection." (PMID 31474993, 2019). "In the process of virus infection and lung damage, the NLRP3 inflammasome pathway is very critical and is closely bound up with IL-1β, IL-33, and IL-18." (PMID 32047436, 2019). "Given that several studies demonstrated protective roles for inflammasomes in various viral infections, our observation that the Nlrp3 inflammasome contributes to MNV-induced lethality in Stat1-/- mice is remarkable." (PMID 31017981, 2019). "An indirect role of MAVS in NLRP3 inflammasome activation by viral dsRNA became apparent, thereby viral infection triggered MAVS-dependent plasma membrane permeabilization driving K+ efflux and NLRP3 activation." (PMID 31540165, 2019). "We propose that in response to viral infection, mtROS is produced by damaged and depolarized mitochondria leading to NLRP3 activation and antiviral inflammation that is driven by IL-1β and IL-18." (PMID 31229895, 2019). "The NLRP3 inflammasome is activated by numerous PAMPs during bacterial, fungal and viral infections, including nigericin, a pore forming toxin derived from Streptomyces hygroscopicus." (PMID 31417575, 2019). "Syk is a tyrosine kinase that is expressed in hematopoietic cells and is involved in NLRP3 activation during fungal infection, viral infection, and in response to LPS stimulation." (PMID 31449558, 2019). "As the NLRP3 inflammasome is activated excessively, it is able to lead to inflammatory response and tissue injury in most viral infection process (including RSV infection) of respiratory tract." (PMID 32047436, 2019).
viral infection (continued). "Nevertheless, the mechanism by which NLRP3 perceives viral infection remains debated and unclear as ion flux induced by the influenza virus-encoded M2 channel, detection of viral RNA, or involvement of a RIPK1–RIPK3–Drp1 signaling pathway have been proposed." (PMID 31024004, 2019). "A virus infection will trigger the assembly of cytosolic multiprotein inflammasome complexes, of which the NLRP3 (NOD-like receptor family, pyrin domain containing three) inflamamasome is the best characterized." (PMID 31849970, 2019). "NOD2 was reported to induce IFNs production following ssRNA transfection and respiratory syncytial and influenza A virus infection, whereas NLRP3 inflammasome activation was reported in viral infections such as IAV, encephalomyocarditis virus, and HCV." (PMID 29734779, 2018). "We demonstrate that neutrophils recruited into the airways during viral infection release mCRAMP, which subsequently activates the NLRP3 inflammasome in alveolar macrophages and triggers IL-1β release." (PMID 29079611, 2018). "For example, NLRP3 plays an important role in viral infections, such as hepatitis C, influenza, and the modified vaccine virus Ankara." (PMID 30349536, 2018). "Of them, nucleotide-binding oligomerization 2 (NOD2) and multi-protein inflammasome complex (i.e., NOD-, LRR-and pyrine domain-containing 3 (NLRP3)) are well studied for sensing the viral infections." (PMID 29734779, 2018). "NACHT, LRR, and PYD domains-containing protein 3 (NLRP3) inflammasome activation and effects during ribonucleic acid (RNA) viral infection are the focus of a wide range of research currently." (PMID 29163496, 2017). "Although NLRP3 inflammasome plays important role in regulating host innate immune response and viral infection, the assembly and activation of NLRP3 inflammasome mediated by viral infection are poorly understood." (PMID 28060938, 2017). "Activating signals for and roles of the NACHT, LRR, and PYD domains-containing protein 3 (NLRP3) inflammasome in ribonucleic acid (RNA) viral infections." (PMID 29163496, 2017). "In fact, NLRP3 inflammasome is very sensitive to ROS and most signals leading to activation of NLRP3 inflammasome, including virus infection, are ROS-dependent." (PMID 27610098, 2016). "This study proposed that Drp1-mediated mitochondrial fission increases mitochondrial damage, resulting in the activation of the NLRP3 inflammasome upon viral infection." (PMID 26489382, 2015). "The most studied of the NLRs in the context of virus infection is the NLR family pyrin domain containing 3 (NLRP3), which upon stimulation leads to the activation of the inflammasome system, with important implications in inflammation." (PMID 26257731, 2015). "HCV products induce intracellular reactive oxygen species and ion flux, both of which trigger the NLRP3 inflammasome during virus infection, whereas potassium efflux is essential for inflammasome signaling by HCV." (PMID 23633957, 2013). "In particular, the NLRP3 inflammasome has been shown to respond to diverse stimuli, including virus infection, and drives proIL-1β processing during flavivirus infection." (PMID 23633957, 2013). "NLRP3 plays an important role in the secretion of proinflammatory cytokines interleukin 1 beta (IL-1β) and IL-18 after viral infections." (PMID 22916014, 2012). "Knowledge of the exact mechanisms by which NLRP3 detects viruses and thereby affects pathogenesis will provide us with a better understanding of viral diseases to design effective interventions and treatments." (PMID 22916014, 2012). "Our results highlight the importance of viroporins, virusencoded transmembrane pore-forming proteins, in recognition of virus infections by NLRP3." (PMID 22916014, 2012). "Furthermore, high glucose level upregulates KDM4B, promoting NLRP3 inflammasome activation and IL-1β secretion, thus aggravating aberrant inflammation during viral infections." (PMID 41703092, 2026).
viral infection (continued). "Drug screening for Hippo and NLRP3/IL-1β pathways may suppress excessive inflammatory responses and intercept NETosis during viral infection." (PMID 40659620, 2025). "Conversely, many viral infections induce autophagy while inhibiting NLRP3 activation." (PMID 41471247, 2025). "Furthermore, RIPK1 inhibition in IBV Conn A5968-infected cells enhanced caspase-1 activity, suggesting a potential crosstalk between RIPK1 and NLRP3 pathways in regulating caspase-1 activity, as described in other viral infection models." (PMID 40284946, 2025). "Viral infection induces mitophagy to inhibit apoptosis and inflammation through NLRP3." (PMID 38441018, 2025). "Although alternative PRRs, such as RIG-I and TLR7, might have an impact on viral infection in some circumstances, our data indicated that NLRP3 was the primary pathway mediated by macrophages in the recognition of IBV." (PMID 40906404, 2025). "Sendai virus and influenza A virus were the earliest viruses to be studied for their ability to activate caspase-1 through NLRP3, thereby promoting the production of IL-1β and IL-18, which provided evidence for the involvement of the NLRP3 inflammasome in the viral infection response." (PMID 40906404, 2025). "In mice, only 2 main inflammasomes, AIM2 and NLRP3, respond to viral infection." (PMID 40825032, 2025). "The mitochondrial antiviral-signaling protein (MAVS) may be important for the formation of the NLRP3 inflammasome in response to viral infection." (PMID 40298704, 2025). "Additionally, the NLRP3 inflammasome inhibitory activity of mefenamic acid plays a crucial role in managing viral infections." (PMID 40851698, 2025). "The NLRP3 inflammasome is critical in host immunity to fungal, bacterial, and viral infections." (PMID 40002971, 2025). "Another important consideration is whether the Hippo-NLRP3-NETosis axis is a universal mechanism across different types of viral infections." (PMID 40659620, 2025). "However, more in-depth research is needed to fully understand the specific mechanism of the NLRP3 inflammasome, and its role and impact in different virus infections." (PMID 38399989, 2024). "The activation of the NLRP3 inflammasome plays a dual role in the process of virus infection." (PMID 38399989, 2024). "Emerging studies indicate that NLRP3-induced pyroptosis contributes to immune defense against various bacterial and viral infections, including Mycobacterium tuberculosis, Staphylococcus pseudintermedius, Mycobacterium abscessus, respiratory syndrome coronavirus 2 and dengue virus." (PMID 39334337, 2024). "To determine how inflammasome activation impacts DENV pathogenesis upon viral infection, we crossed Casp1/11-/- or Nlrp3-/- separately with Ifnar-/- mice to generate Casp1/11-/ -x Ifnar-/- and Nlrp3-/-x Ifnar-/- double-deficient mice and infected them with DENV2 D220." (PMID 38662771, 2024). "We conducted in vitro experiments to assess mitochondrial damage in cells following viral infection, measure the expression levels of the NLRP3 inflammasome and IL-1β, and evaluate the activation pathway of the NLRP3 inflammasome in PEDV-infected porcine small intestinal epithelial cells." (PMID 39728983, 2024). "Upon recognition of these patterns, the NLRP3 inflammasome undergoes activation, leading to the release of proinflammatory cytokines, which in turn initiate the host’s immune response to combat the viral infection." (PMID 39769082, 2024). "Thus, why NLRP3 has a double-sided effect on virus infection mainly depends on the game between virus and host immunity." (PMID 38705479, 2024). "To examine whether 3aCoV2 activates the NLRP3 inflammasome during viral infection, we established a RAW 264.7 murine macrophage cell line stably expressing hACE2-Flag and ASC, the adaptor protein downstream of NLRP3." (PMID 38798602, 2024). "The NLRP3 inflammasome is activated following viral infection." (PMID 38247540, 2024). "NLRP3 plays a potential role in a variety of viral infections." (PMID 38399989, 2024).
viral infection (continued). "This section aims to provide a comprehensive understanding of the intricate relationship between the Nod-like receptor protein 3 (NLRP3) inflammasome, viral infections, and mitochondrial dynamics, offering insights into the complex interplay between these biological processes." (PMID 39769082, 2024). "As consequence of virus infection and the immune-defense response, increased activation of NF-κB/NLRP3 inflammasome pathways, vasoactive peptides, cytokines, NETosis, and the complement system, finally damage endothelial vasculature and stimulate coagulation mediators." (PMID 38378550, 2024). "The blockade of CLEC5A has been reported to decrease Nlrp3 expression after virus infection." (PMID 39443966, 2024). "Investigations into these inhibitors have revealed their capacity to modulate the NLRP3 pathway, effectively attenuating the exaggerated inflammatory response prompted by viral infection, thereby curtailing tissue damage, and fostering improved patient prognoses." (PMID 38399989, 2024). "The activation of the NLRP3 inflammasome during viral infections has been extensively studied." (PMID 39769082, 2024). "These examples suggest that NLRP3 inflammasomes regulate the inflammatory response and affect immune cell function in different viral infections and may have potential antivirus effects." (PMID 38399989, 2024). "ZBP1 is also a crucial regulator of the NLRP3 inflammasome in response to viral infection." (PMID 39475237, 2024). "Therefore, we studied the specific process involved in the secretion of the inflammatory cytokine IL-1β after the PEDV infection of IPEC-J2 cells, and we found that viral infection activated the NLRP3 inflammasome in this context." (PMID 39728983, 2024). "These suggest that NLRP3 may play different roles in different viral infections in different cells, and further discussion is needed." (PMID 37465759, 2023). "Interestingly, we also detected in SARS-CoV-2-infected lung tissues, some syncytia that expressed macrophage marker, CD68, NLRP3 and viral RNA, revealing a potential link between NLRP3 expression and viral infection." (PMID 37920468, 2023). "There is a complex relationship between viral infection and NLRP3 inflammasome activation." (PMID 37243164, 2023). "However, temporal inhibition of NLRP3 with MCC950 has been shown to have detrimental effects on viral infection if induced too early in infection, highlighting the requirement for NLRP3 to induce a protective immune response." (PMID 37950278, 2023). "In this review, we present a variety of regulatory mechanisms and functions of the NLRP3 inflammasome upon RNA viral infection and demonstrate multiple therapeutic strategies that target the NLRP3 inflammasome for anti-inflammatory effects in viral infection." (PMID 38249297, 2023). "Therefore, KCH reduces the expression of the NLRP3 inflammasome complex, which is increased by viral infection." (PMID 38001788, 2023). "However, there are also some studies have shown that NLRP3 seems to induce inflammatory response during viral infection." (PMID 37465759, 2023). "The findings of this study shed light on a novel mechanism of CVB3 in suppressing NLRP3 inflammasome activation, and may contribute to the understanding of the relationship between viral infection and innate immune responses." (PMID 37243164, 2023). "We briefly discuss the clinical significance of NLRP3 inflammasome activation in viral disease." (PMID 38249297, 2023). "Thus, NLRP3 is considered to be one of the most important inflammasomes against viral infection and contributes greatly to the stimulation of the host’s natural antiviral immunity." (PMID 37608944, 2023). "Furthermore, NLRP3 has the capacity to interact with Mitofusin-2 in the context of viral infections." (PMID 37892135, 2023).
viral infection (continued). "Among these, the NOD-, LRR- and pyrin domain-containing protein 3 (NLRP3) inflammasome acts as a classic pyroptosis mediator that can be activated by various types of viral infections, including Zika, influenza A (IAV), and hepatitis C viruses (HCV) (15, –, 18)." (PMID 35758658, 2022). "Thus, the dampened functionality of NLRP3 and loss of the PYHIN gene family dramatically affects the activation of inflammasomes, thereby limiting the inflammatory state induced by viral infection in the described bat species." (PMID 35875684, 2022). "It should also be investigated whether the formation of RTC by viral infection is a common mechanism of NLRP3 activation." (PMID 35758658, 2022). "However, there was a reduced enhancement of WBC and monocytes before viral infection and at 4 dpi in Nlrp3-KO mice compared to C57BL/6J mice." (PMID 34979342, 2022). "Although the mechanism of NLRP3 inflammasome activation remains unknown in endothelial cells, studies indicated that NF-κB, which is activated upon a range of stimuli during viral infection, transcribes effector genes NLRP3 and pro-IL-1β." (PMID 35587188, 2022). "NLRP3 inflammasome is essential for host immune defense against viral infections." (PMID 35958608, 2022). "Additionally, DDX19A and DHX33 promote activation of the NLRP3 inflammasome in response to viral infections." (PMID 35626643, 2022). "Despite the contradictory response depending on the type of viral infection, the importance of NLRP3-dependent inflammasome in various viral infections is contiguous and therefore an interesting target for manipulation aiming at improved disease outcomes, including in CHIKV infection." (PMID 36189282, 2022). "NLRP3 inflammasome mainly controls interleukin-1β (IL-1β) secretion, leading to cell death called pyroptosis constituting a major antiviral host defense and inflammatory diseases upon viral infection." (PMID 35300578, 2022). "Viral infections can trigger IL-1β expression by activating the NLRP3 inflammasome or MAPK signaling pathway, while different viruses may induce IL-1β expression through different signaling molecules." (PMID 35854395, 2022). "In addition, SARS-CoV-2 infection induced NLRP3 expression and such an induction was also observed in other types of virus infection." (PMID 34979342, 2022). "Our study indicates that UCHL5 is also important for NLRP3 activation during viral infection." (PMID 34431717, 2021). "This indicates that SGs might also interfere with the assembly and activation of the NLRP3 inflammasome during virus infection." (PMID 33766561, 2021). "The main pathways involved in virus infections include the NLRP3, IFI16, and AIM2 pathways." (PMID 34595244, 2021). "The modulation of NLRP3 inflammasome activity may be a promising approach to counteract viral diseases and the subsequent inflammatory reactions." (PMID 34209586, 2021). "This phenomenon can be explained by the high level of ROS for the activation of SARS-CoV 3a-induced NLRP3 inflammasome because virus infection activates nod-like pyrin domain-containing 3 (NLRP3) family, which is activating the release of ROS from damaged mitochondria." (PMID 33918184, 2021). "During viral infection, activation of the NLRP3 inflammasome by integrating multiple cellular and molecular signaling implicates robust inflammation, fibroblast proliferation, activation of myofibroblast, matrix deposition, and aberrant epithelial-mesenchymal function." (PMID 34638790, 2021). "However, viral infection can induce IL-1β–mediated inflammation through NLRP3-independent mechanisms." (PMID 34638790, 2021). "We then examined whether other viral infections can trigger Golgi fragmentation through NLRP3 and, in particular, whether this occurs in monocytic cell types, in which the inflammasome has been well studied." (PMID 33208442, 2021).